DNMT1 (DNA methyltransferase 1)
Diseases named in the same sentence as DNMT1 in open-access papers (continued):
Sharing a sentence is not in itself a finding about the gene and the disease.
folate deficiency (6 papers, 2017 to 2024). A nutritional condition produced by a deficiency of FOLIC ACID in the diet. "In another study related to folate deficiency, the expression of DNMT1 and DNMT3A were found to be up-regulated in the uteruses of pseudo-pregnant mice." (PMID 31772242, 2019). "Folate deficiency (FD) led to an increase in the mRNA levels of DNMT1 in the kidney (female), however, with folate over-supplementation (FO) levels were not changed when compared to folate normal (FN)." (PMID 31772242, 2019). "B12 deficiency in combination with folate deficiency (BDFD) as well as over-supplementation (BDFO) led to increased mRNA levels of DNMT1 in the brain and liver whereas levels were decreased in the kidney (BDFN and BDFO) along with an increase in placenta (BDFN and BDFD) as compared to BNFN." (PMID 31772242, 2019). "Folic acid deficiency further downregulated DNMT1 and DNMT3a mRNA levels in DM mice." (PMID 28422052, 2017). "Folate deficiency combined with B12 deficiency (BDFD) increased the mRNA levels of DNMT1 all fetal tissues regardless of sex whereas in combination with the state of B12 normal (BNFD) the expression of DNMT1 was increased in the liver and the brain (female) in comparison to BNFN." (PMID 31772242, 2019). "Folate deficiency combined with either state of B12 (BNFD, BDFD, BOFD) resulted in an increase in the transcript levels of DNMT1 as compared to BNFN." (PMID 31772242, 2019). "Hence, the gestation associated increased global methylation might be due to increased expression of DNMT1 and DNMT3A, and abnormally high DNMTs expression in association with folate deficiency results in the abnormal global methylation in preeclampsia." (PMID 35578613, 2022).
hyperhomocysteinemia (6 papers, 2013 to 2023). A serious metabolic condition caused by mutations in the MTHFR gene, medications, or nutritional deficiency. "By comparison, hyperhomocysteinemia associated with increased SAH levels reduced the activity of DNMT1 only by 30%." (PMID 26974671, 2016). "The expression of DNMT1 mRNA, which the DFV down-regulated, was increased by eritadenine and dose-dependently increased by L. edodes (5, 10 and 20%) in the mice with hyperhomocysteinemia compared with the level in the NC group." (PMID 24137209, 2013).
infiltrating ductal breast carcinoma (6 papers, 2012 to 2021). "Epigenetic regulation of DNMT1 was assessed in 85 invasive ductal carcinomas from BRCA1 mutation carriers." (PMID 24502362, 2014). "To date, the DNMT1 rs2228611 SNP has been associated with sporadic infiltrating ductal breast carcinoma among Chinese Han women in the Heilongjiang Province." (PMID 23666104, 2013). "Therefore, 10 pairs of paraffin embedded sections including both tumor and their adjacent normal tissues derived from patients suffering invasive ductal carcinoma of different stages and subtypes were immunostained by anti-DNMT1 antibody." (PMID 29416775, 2018).
metastatic carcinoma (6 papers, 2015 to 2022). A carcinoma which has spread from the original site of growth to another anatomic site. "(2013) revealed that in PCa, Dnmt1 nuclear staining significantly increased from normal to metastatic cancer." (PMID 30628163, 2019).
metastatic tumors (6 papers, 2022 to 2025). "Taken together, these results suggest that TQ exerts protective effects against BC risk and reduces the development of metastatic tumors in vivo through a mechanism involving a downregulation of DNMT1, which leads to the inhibition of proliferation and the induction of apoptosis of tumor cells." (PMID 38257347, 2024). "As the expression of eccDNA DNMT1circle10302690-10302961 and DNMT1 mRNA both decreased in metastatic tumors of HGSOC, we assumed that DNMT1circle10302690-10302961 may also have such prognostic value." (PMID 35418185, 2022).
osteoarthritis (6 papers, 2015 to 2023). A noninflammatory degenerative joint disease occurring chiefly in older persons, characterized by degeneration of the articular cartilage, hypertrophy of bone at the margins and changes in the synovial membrane. "Based on the effectiveness, the target DNMT1 was selected to identify the active constituents of DD in ameliorating osteoarthritis, presumably by preservation of PPARγ expression." (PMID 36506533, 2022). "They show comparable levels to the observed in osteoarthritis (OA) FLS, but DNMT1 expression is markedly downregulated by incubation with small amounts of inflammatory cytokines." (PMID 26330155, 2015).
small cell lung carcinoma (6 papers, 2017 to 2025). Small cell lung cancer (SCLC) is a highly aggressive malignant neoplasm, accounting for 10-15% of lung cancer cases, characterized byrapid growth, and early metastasis. "In small cell lung cancer, DNA methyltransferase 1 (DNMT1) inhibits CCL2 expression by adding methyl groups to CpG islands in the promoter region of CCL2 gene, preventing TF binding." (PMID 41341593, 2025). "The epigenetic silencing of the CCL2 gene by DNA methyltransferase 1 (DNMT1)-mediated DNA methylation in the enhancer region of the gene has been shown to enhance the development of small cell lung cancer by repressing the infiltration of cytotoxic macrophages." (PMID 37208442, 2023). "In both non-small-cell lung cancer (NSCLC) and small-cell lung cancer (SCLC) subtypes, increasing levels of DNA methylation are observed in dDTC, predominantly mediated by DNA methyltransferase 1 (DNMT1)." (PMID 41303477, 2025).
squamous cell carcinoma (6 papers, 2016 to 2024). A carcinoma arising from squamous epithelial cells. "Among these squamous cell carcinomas, increased mRNA expression of both DNMT1 and Survivin has been shown in 4 of them (#6, #11, #15, and #20)." (PMID 27177222, 2016).
Stroke (6 papers, 2013 to 2025). Sudden impairment of blood flow to a part of the brain due to occlusion or rupture of an artery to the brain. "DNMT1 was also associated with microglial polarization after stroke." (PMID 40356977, 2025). "The investigated interval, 24 h, when DNMT1 is expressed, corresponds to the acute post-stroke period." (PMID 34830365, 2021). "The levels of DNMT3a, DNMT3b, and DNMT1 in the contralesional cortex after a stroke (p < 0.001, n = 6) significantly increased." (PMID 29997355, 2018). "In another animal model of photothrombotic stroke (PTS), the level of DNMT1 was increased in the nuclear fraction of neurons and in the cytoplasmic fraction of astrocytes in the penumbra tissue at 24 h after PTS induction; furthermore, apoptosis was induced." (PMID 36142283, 2022).
asthma (5 papers, 2019 to 2025). "DNMT1 and DNMT3a, as DNA methyltransferase enzymes as writer proteins, play a key role in methylating DNA, contributing to the epigenetic alterations associated with asthma pathogenesis." (PMID 41008562, 2025). "These insights are essential for understanding the role of DNMT1 DNMT3a in epigenetic regulation relevant to asthma pathogenesis." (PMID 41008562, 2025). "Using 5-azacytidine to inhibit DNMT1 in a murine model of asthma augmented numbers of Treg cells and effectively reduced airway inflammation." (PMID 30782202, 2019).
autism (5 papers, 2013 to 2025). Persistent deficits in social interaction and communication and interaction as well as a markedly restricted repertoire of activity and interest as well as repetitive patterns of behavior. "Indeed, alterations in DNA methylation has been linked to several neurodevelopmental disorders such as autism and schizophrenia, and mutations in DNMT1 lead to a broad spectrum of neurological disorders that include cognitive disturbances and psychiatric manifestations." (PMID 31320637, 2019). "This consistent change in expression patterns supports the hypothesis that Arrb2 contributes to autism pathogenesis by regulating Myh9, Dnmt1, and Brd4, although differently in different tissues." (PMID 40428426, 2025).
B-cell lymphoma (5 papers, 2014 to 2022). "The DNA methylation of CpG island causes the reduction of miR-342-3p, which is resulted in failure to operate tumor suppressor function by inhibiting pro-survival autophagy by targeting MAP1LC3B and DNMT1 in B cell lymphoma." (PMID 34526970, 2021). "In this paper, we investigated the expression of DNMT family members (DNMT1, DNMT3a/b) in primary cases of aggressive B-cell lymphomas of HIV-positive subjects." (PMID 25705251, 2014). "Our results show that DNMT1, DNMT3a/b are up-regulated in B-cell lymphomas, and that this relies on down-regulation of specific miRNAs." (PMID 25705251, 2014). "Therefore, methylation-mediated silencing of miR-342-3p leads to upregulation of DNMT1 in B-cell lymphoma with the potential of promoter hypermethylation and repression of multiple tumor suppressor genes." (PMID 33076962, 2020). "Our results confirmed the activation of DNMT1 by HIV in vivo, and reported for the first time a marked up-regulation of DNMT3a and DNMT3b in HIV-positive aggressive B-cell lymphomas." (PMID 25705251, 2014). "HIV has been reported to induce the expression of DNMT1 in vitro, but still no information is available about the mechanisms regulating DNMT expression in HIV-related B-cell lymphomas." (PMID 25705251, 2014). "Finally, given that DNMT1 is a known target of miR-342-3p, herein we showed that over-expression of miR-342-3p led to promoter hypomethylation and re-expression of tumor suppressor gene E-CAD in B-cell lymphoma cells." (PMID 33076962, 2020). "Instead, HDAC1 and DNMT1, the main known HDAC and DNMT factors in cancer have highest expression in hematopoietic malignancies, especially the B-cell lymphoma in the pan-cancer expression analysis (cBioportal) which may be the reason of the effectiveness of HDACi and DNMTi in treating these cancers." (PMID 28642588, 2017). "HIV is reported to induce the expression of DNMT1 in vitro, though no information is available about its effect on DNMT3a/b, and about their expression in HIV-positive B-cell lymphomas." (PMID 25705251, 2014).
cutaneous melanoma (5 papers, 2015 to 2023). A primary melanoma arising from atypical melanocytes in the skin. "To investigate the DNMT1 mRNA expression in early and advanced stage cutaneous melanoma, we interrogated two FFPE tissue microarray datasets (GSE3189 and GSE8401)." (PMID 34572918, 2021). "DNA methyltransferase-1 (DNMT1) is a key epigenetic regulatory protein of gene expression in cutaneous melanoma." (PMID 34572918, 2021).
endothelial dysfunction (5 papers, 2017 to 2024). In vascular diseases, endothelial dysfunction is a systemic pathological state of the endothelium (the inner lining of blood vessels) and can be broadly defined as an imbalance between vasodilating and vasoconstricting substances produced by (or acting on) the endothelium. "Moreover, although we and others have previously shown a role of DNMT1 in mediating the disturbed flow-initiated endothelial dysfunction 15, 19-21, no study has been reported related to the utilization of conditional EC Dnmt1 knockout mice in the literature." (PMID 37649604, 2023).
epilepsy (5 papers, 2021 to 2025). A brain disorder characterized by episodes of abnormally increased neuronal discharge resulting in transient episodes of sensory or motor neurological dysfunction, or psychic dysfunction. "Moreover, both overexpression and deficiency of DNMT1 may lead to dysregulation of neural differentiation in epilepsy development." (PMID 39753851, 2025). "Vagus nerve stimulation (VNS) reduces the number of SRSs in rats with epilepsy with concomitant decrease of 5‐mC, DNMT1, DNMT3A, METTL3, and METTL14, as well as increase of 5‐hmC." (PMID 40534269, 2025). "We found that CDC25B, DNMT1, GZMA, MTX1, and SSH2 expression decreases epilepsy risk, whereas FGD3, RAF1, and SH3BP5L increase it." (PMID 39753851, 2025). "We conclude that VNS reduces the number of SRSs in a rat model of epilepsy, concurrently reducing the expression of 5‐mC, DNMT1, DNMT3A, METTL3, and METTL14, as well as the increase of 5‐hmC." (PMID 40534269, 2025). "Apart from DNMT1, the roles of the other key genes in epilepsy have remained relatively scarce." (PMID 39753851, 2025). "DNMT1 has garnered attention for its role in epigenetic modifications in epilepsy." (PMID 39753851, 2025). "DNA/RNA methylation through the DNMT1/3A and METTL3/METTL14 pathway might be therefore a potential target of VNS therapy for the treatment of epilepsy." (PMID 40534269, 2025).
Hodgkins lymphoma (5 papers, 2016 to 2021). A heterogeneous group of malignant lymphoid neoplasms of B-cell origin characterized histologically by the presence of Hodgkin and Reed-Sternberg (HRS) cells in the vast majority of cases. "DNMT1 and DNMT3B expression was shown to be downregulated in EBV-infected lymphoblastoid cells and Hodgkin’s lymphoma cell lines, which is distinct from that observed for EBVaGC and EBV-positive NPC." (PMID 29438328, 2018).
ICF syndrome (5 papers, 2015 to 2023). "Hence, we propose that hypomethylation due to inefficient DNMT1/UHRF1 recruitment at pericentromeric repeats by defects in the CDCA7/HELLS complex could induce pericentromeric instability, which may explain a part of the molecular pathogenesis of ICF syndrome." (PMID 33082427, 2020).
ischemic stroke (5 papers, 2018 to 2025). A stroke disorder caused by obstruction of blood flow to the brain, due to thrombotic (local blood clot formation) or embolic (due to a blood clot or other material traveling from another site) event. "This suggests the involvement of DNMT1 in apoptosis of penumbra cells after ischemic stroke." (PMID 34830365, 2021).
kidney (5 papers, 2016 to 2022). "We then tested DNMT1 regulation in the context of kidney injuries." (PMID 35765066, 2022). "RAD9 was epigenetically regulated by DNMT1 and DNMT3B, and subsequent RAD9 overproduction promotes prostate tumorigenesis by targeting hypermethylation." (PMID 34970791, 2022). "RAD9 was epigenetically regulated by DNMT1 and DNMT3B, and subsequent RAD9 overproduction promoted prostate tumorigenesis by targeting hypermethylation." (PMID 34904288, 2022).
lung squamous cell carcinoma (5 papers, 2010 to 2022). "In lung squamous cells carcinoma, DNMT1 super-expression is involved with poor prognosis and over-expression of DNMT1 and DNMT3b is correlated with hypermethylation of tumor suppressor genes." (PMID 21860617, 2012). "The high expression of DNMT1 was a common phenomenon in lung squamous cell carcinoma and adenocarcinoma." (PMID 20840813, 2010). "The expressions of DNMT1 and β-catenin were examined in 84 lung squamous cell carcinoma and adenocarcinoma tissues and corresponding normal lung tissues using tissue microarray and immunohistochemistry." (PMID 20840813, 2010). "In lung squamous cell carcinoma, DNMT1 expression was negatively related with PLK2 level." (PMID 34080290, 2021).
medulloblastoma (5 papers, 2015 to 2023). A malignant, invasive embryonal neoplasm arising from the cerebellum. "Five genes were identified, including GLI1, which was reported to be regulated by the UHRF1/DNMT1 complex in medulloblastoma." (PMID 37380646, 2023). "Downregulation of ROCK1 and DNMT1 upon miR-148a expression is therefore likely to contribute to miR-148a's tumor-suppressive effect on medulloblastoma cells." (PMID 26097868, 2015). "Expression of ROCK1 and DNMT1, two known miR-148a targets, was found to be downregulated upon miR-148a expression in medulloblastoma cells." (PMID 26097868, 2015). "At first glance, our new model appears to conflict with our recent observation that heterozygosity for Dnmt1 delayed (instead of accelerated) the growth of medulloblastoma in heterozygous Ptch mice." (PMID 25823816, 2015). "Downregulation of DNMT1 expression has been shown to reduce tumor incidence in the Ptch1 heterozygous knock-out mice, a mouse model of SHH subgroup medulloblastomas." (PMID 26097868, 2015). "The oncogenic effect of mutations in the fusion genes such as ARID1A, PVT1, GFI1, MYCN, DNMT1, and TET3 has been identified in various tumors including medulloblastomas to regulate tumorigenesis, suggesting that the predicted inframe fusion proteins may possess oncogenic potential." (PMID 33681213, 2021).
myocardial infarction (5 papers, 2019 to 2024). Gross necrosis of the myocardium, as a result of interruption of the blood supply to the area, as in coronary thrombosis. "In rats with diabetes mellitus and myocardial infarction, downregulation of DNMT1 and DNMT3A inhibits the methylation of the inophosphine promoter, which in turn leads to impaired sarcoplasmic reticulum calcium uptake, decreased myocardial contractility, and worsened cardiac insufficiency." (PMID 38584203, 2024). "Additionally, GWAS have associated single nucleotide polymorphisms (SNPs) in miR-140-5p gene targets such as SEPT2 (SEPTIN2) with T1DM, DNMT1 with CVD and HDAC4 with increased susceptibility to myocardial infarction following coronary artery bypass surgery." (PMID 36277770, 2022). "The down-regulation of DNMT1 expression and the expression of myofibroblast marker a-SMA were detected in the myocardial infarction region, but the degree of a-SMA methylation decreased." (PMID 38584203, 2024). "In cardiac, Kcnq1ot1 recruits DNA methyltransferase 1 (DNMT1) to the RUNX3 promoter region and inhibit Runx3 expression, regulating the proliferation and apoptosis of CMEC and induces inflammatory response during myocardial infarction." (PMID 34604208, 2021).
oral squamous cell carcinoma (5 papers, 2023 to 2025). "For instance, in oral squamous cell carcinoma, DNMT1 knockdown induces global hypomethylation, inactivating PI3K-AKT and CDK2-Rb signaling, and cooperating with GSK3β inactivation to suppress tumorigenicity." (PMID 41381440, 2025). "We previously identified DNMT1 as a potential candidate target for oral squamous cell carcinoma (OSCC)." (PMID 38755637, 2024). "In oral squamous cell carcinoma, the expression levels of DNMT1 were also correlated with the immunosuppressive molecules and tumor-promoters such as PD-L1, indicating a worse prognosis." (PMID 37686163, 2023). "In oral squamous cell carcinoma (OSCC), a subtype of HNSCC, LINC00460 is overexpressed and recruits DNA methyltransferase 1 (DNMT1) to the miR-612 promoter, promoting DNA methylation and silencing of this tumor-suppressive microRNA." (PMID 41020820, 2025).
polycystic ovary syndrome (5 papers, 2016 to 2025). A disorder that manifests as multiple cysts on the ovaries. "Geng and colleagues explored the contribution of DNMT1 in the pathophysiology of polycystic ovary syndrome (PCOS)." (PMID 40387409, 2025). "In polycystic ovary syndrome (PCOS) patients, DNMT1-dependent CDKN1A promoter hypomethylation inhibits the proliferation and growth of GCs." (PMID 34175894, 2021). "In polycystic ovary syndrome, lnc-MAP3K13-7:1 inhibited the proliferation of ovarian GCs via DNMT1 downregulation mediated by CDKN1A promoter hypomethylation." (PMID 40214477, 2025).